SLC35F2 (solute carrier family 35 member F2)
Description:
High affinity plasma membrane importer of the nucleobase queuine (q) and its nucleoside queuosine (Q), two bacterially derived micronutrients acquired from the gut microbiome and diet. Following cellular uptake, queuosine is incorporated at the wobble base (position 34) of tRNAs that decode histidine, tyrosine, aspartate, and asparagine codons, which is important for efficient translation. Also involved in choline transport, although the underlying transport mechanism remains to be elucidated.
Synonyms: FLJ13018; HSNOV1
Tractability: Antibody: UniProt predicts a signal peptide or a membrane-spanning region. PROTAC: ubiquitination databases record sites on it; its protein half-life has been measured.
Gene: Protein-coding gene on chromosome 11 (107,790,991 to 107,928,293, reverse strand). Ensembl gene ENSG00000110660.
Subcellular location: Cell membrane; Golgi apparatus membrane
Subcellular location (Human Protein Atlas): Golgi apparatus
Gene Ontology:
Molecular function: choline transmembrane transporter activity; transmembrane transporter activity
Biological process: choline transport; tRNA queuosine(34) biosynthetic process from salvaged queuine; tRNA queuosine(34) biosynthetic process from salvaged queuosine or its precursors; transmembrane transport
Cellular component: Golgi membrane; plasma membrane; membrane
Genetic constraint (gnomAD): Loss-of-function variants: 20 observed, 32.76 expected, observed/expected ratio (o/e) 0.61, 90% interval 0.43 to 0.89. The upper end of that interval is the gene's LOEUF score, 0.89, which puts it in group 3 of 6, group 1 being the genes least tolerant of losing a copy. Missense variants: 340 observed, 401.4 expected, observed/expected ratio (o/e) 0.85, 90% interval 0.77 to 0.93. Synonymous variants: 143 observed, 159.83 expected, observed/expected ratio (o/e) 0.89, 90% interval 0.78 to 1.03.
Homologues: Orthologues: chimpanzee SLC35F2 (99% identical), macaque SLC35F2 (98% identical), pig SLC35F2 (92% identical), dog SLC35F2 (91% identical), rat Slc35f2 (90% identical), mouse Slc35f2 (90% identical), rabbit SLC35F2 (84% identical), guinea pig SLC35F2 (76% identical), tropical clawed frog slc35f2 (65% identical), zebrafish slc35f2l (55% identical), zebrafish slc35f2 (55% identical), Caenorhabditis elegans Y73E7A.3 (40% identical). Paralogues in human: SLC35F1 (55% identical).
Diseases named in the same sentence as SLC35F2 in open-access papers:
SLC35F2 is named in the same sentence as 20 diseases in open-access papers, as found by Europe PMC text mining. Sharing a sentence is not in itself a finding about the gene and the disease. The quoted sentences say what the papers report.
breast carcinoma (5 papers, 2017 to 2026). "Moreover, USP32 control over the stability of the SLC35F2 protein is linked to YM155 resistance in breast cancer." (PMID 39030175, 2024). "USP32 also contributes to the development of YM155 drug resistance in breast cancers by downregulating SLC35F2 protein expression." (PMID 41356798, 2026). "The uptake of the anti-cancer drug candidate YM155 by breast cancer cells is controlled by the expression of a solute carrier protein called SLC35F2." (PMID 37679322, 2023). "USP32 was highly upregulated in breast cancer while SLC35F2 were significantly lower in these tissues." (PMID 34815782, 2021). "The strongest eQTL associations were observed in the breast cancer tissue dataset BC241 for the SLC35F2 gene (rs181187590, p = 1.4 × 10−5, r2 = 0.08, i.e., 8 % of the variation in SLC35F2 expression was attributable to this SNP)." (PMID 27796716, 2017). "Researchers further found that the direct binding of USP32 and SLC35F2 in the endoplasmic reticulum could negatively regulate the stability of SLC35F2 and promote drug resistance to YM155 in breast cancer cells." (PMID 37679322, 2023). "Therefore, inhibition of USP32 can increase the protein expression of SLC35F2 and improve the chemotherapeutic effect of YM155 on breast cancer, opening up a new pathway for clinical drug resistance treatment." (PMID 37679322, 2023).
lung carcinoma (5 papers, 2013 to 2022). "Knockdown of SLC35F2 in H1299 lung cancer cells reduced their proliferation, migration, and invasion, likewise supporting the role of SLC35F2 as an oncogene in lung cancer." (PMID 33418944, 2021). "The expression patterns of USP32 and SLC35F2 in human breast (n = 21), colon (n = 32), and lung cancers (n = 32) obtained from ISU Abxis tissue microarray were subjected to immunohistochemistry staining." (PMID 34815782, 2021). "Here we used RNAi to silence SLC35F2 in H1299 cell line, and studied the effect of the SLC35F2 gene on the biological behavior of lung cancer cell line." (PMID 23879892, 2013). "To develop further studies on the biological functions of SLC35F2, we constructed SLC35F2 recombinant RNAi lenti-virus vectors, and got transfected H1299 lung cancer cells in which the expression of SLC35F2 was stably inhibited by RNAi." (PMID 23879892, 2013). "The migration and invasion capacities of the cells were reduced after the SLC35F2 gene was inhibited, which suggests that SLC35F2 plays an important role in the migration and invasion of lung cancer cells to peripheral tissues." (PMID 23879892, 2013). "The effect of SLC35F2 silencing on the proliferation of H1299 lung cancer cells was determined by CCK-8 assay." (PMID 23879892, 2013). "Here we are to investigate the effect of the SLC35F2 gene on the biological behavior of human lung cancer cell line H1299." (PMID 23879892, 2013). "For the first time, we have identified the influence of SLC35F2 on the biological behavior of H1299 lung cancer cell line in this study." (PMID 23879892, 2013). "However, SLC35F2 was highly upregulated in colon and lung cancer tissues and relative low levels of USP32 were observed in the respective tissues." (PMID 34815782, 2021). "The results are consistent with our previous studies, and showed SLC35F2 might be a potential oncogene in lung cancer." (PMID 23879892, 2013). "SLC35F2, also known as lung squamous cell cancer related protein (LSCC-3), is also upregulated in non-small cell lung cancer with knockdown of SLC35F2 in lung cancer cell lines reducing proliferation and invasion, although whether this relates to nucleotide transport is unknown." (PMID 28350329, 2017). "RNA interference-mediated downregulation of SLC35F2 expression by lentiviral vector can attenuate the proliferation, migration and invasion capacities of H1299 cells, which suggests that SLC35F2 may be a potential oncogene of lung cancer." (PMID 23879892, 2013). "SLC35F2 might be a potential target for lung cancer therapy in the future." (PMID 23879892, 2013).
non-small cell lung carcinoma (4 papers, 2017 to 2022). A group of at least three distinct histological types of lung cancer, including non-small cell squamous cell carcinoma, adenocarcinoma, and large cell carcinoma. "In contrast, SLC35F2 is expressed highly in bladder 40, papillary thyroid 41, lung 42, and non-small-cell lung cancer." (PMID 34815782, 2021). "Patients with non-small cell lung carcinoma (NSCLC) showed high expression levels of SLC35F2, which correlated with pathological staging and suggested the use of SLC35F2 as a prognostic marker in NSCLC." (PMID 33418944, 2021).
ataxia telangiectasia (3 papers, 2013 to 2022). Ataxia-telangiectasia is the association of severe combined immunodeficiency (affecting mainly the humoral immune response) with progressive cerebellar ataxia. "SLC35F2 was first described in ataxia-telangiectasia and some studies have shown that SLC35F2 is involved in the development of various cancer types." (PMID 33418944, 2021).
Bladder Cancer (2 papers, 2021 to 2022). "Moreover, knockdown of SLC35F2 repressed the growth of bladder cancer cells in the monolayer and spheroid model and suppressed migration and invasion of bladder cancer cells." (PMID 33418944, 2021). "Furthermore, we showed that knockdown of SLC35F2 repressed the migration and invasion in T24 and Cal29 cells, suggesting that SLC35F2 contributes to the migration and invasion of bladder cancer cells." (PMID 33418944, 2021). "In conclusion, we suggest that SLC35F2 is involved in bladder cancer progression and might provide a new therapeutic approach, for example, by the anti-cancer drug YM155, a cargo of the SLC35F2 transporter." (PMID 33418944, 2021).
neuroblastoma (2 papers, 2016 to 2020). Neuroblastoma (NB) is the most common solid, extracranial childhood tumor. "This notion is further supported by our finding that SLC35F2 depletion increases the resistance of ABCB1-expressing neuroblastoma cells." (PMID 27735941, 2016). "Reasons for this may include that survivin is not in all cell lines the major therapeutic target of YM155 as it is in neuroblastoma cells and/or that off-target resistance mechanisms, such as ABCB1 and SLC35F2 expression, may affect YM155 efficacy independently of the survivin status." (PMID 32357518, 2020).
papillary thyroid carcinoma (2 papers, 2021 to 2023). "In addition, high levels of SLC35F2 were positively correlated with progression of papillary thyroid carcinoma (PTC) and knockdown of SLC35F2 suppressed the malignant phenotype of PTC cells in vitro and in vivo." (PMID 33418944, 2021). "Additionally, SLC35F2 has been found to promote the progression of papillary thyroid carcinoma." (PMID 37869713, 2023).
prostate carcinoma (2 papers, 2017 to 2021). A carcinoma that arises from epithelial cells of the prostate gland. "In particular, eligibility requirements for the prostate cancer trial required castrate levels of serum testosterone (≤50 ng/mL), and decreased AR-activity may have caused a downregulation of SLC35F2 that prevented effective tumor uptake of YM155." (PMID 28350329, 2017). "Analysis of ~150 castration-resistant prostate cancer metastases revealed that SLC35F2 expression correlated with AR activity score, but that a subset of patient tumors had high expression of the transporter regardless of AR status." (PMID 28350329, 2017). "Using high-throughput drug screening, we found that YM155 synergized with high-dose androgen therapy in prostate cancer cells, and that this interaction was mediated by direct transcriptional upregulation of SLC35F2 by AR." (PMID 28350329, 2017). "The emerging role of high-testosterone (T) therapy in prostate cancer makes AR-induced sensitivity to SLC35F2 transported therapeutics clinically relevant." (PMID 28350329, 2017). "Moreover, in prostate cancer, SLC35F2 seems to play a role, as it was highly expressed, directly upregulated by the androgen receptor (AR) activation and crucially involved in the sensitivity of prostate cancer cells to YM155." (PMID 33418944, 2021). "It has been shown that SLC35F2 is highly expressed in NSCLC, PTC, prostate cancer, and BC, and the authors suggest that high SLC35F2 expression is correlated with cancer progression." (PMID 33418944, 2021). "Consistent with the concentrative, antiport mechanism of SLC35-nucleotide family transporters, tumor models with high levels of SLC35F2, such as the PC3 prostate cancer cell line, are able to accumulate high intratumoral levels of YM155." (PMID 28350329, 2017). "Thus, high-dose testosterone therapy may enhance sensitivity to YM155 in castrate prostate cancer patients with low tumoral SLC35F2 expression by inducing SLC35F2, while high SLC35F2 expression at baseline serving as biomarker to select patients who may be immediate candidates for YM155 treatment." (PMID 28350329, 2017).
pancreatic cancer (1 paper, 2022). "We aimed to explore the role of Solute Carrier Family 35 Member F2 (SLC35F2) in pancreatic cancer (PCa) and to further study whether SLC35F2 regulates cisplatin resistance of PCa cells through the modulation of RNA binding motif protein 14 (RBM14) expression." (PMID 35669242, 2022).
prostate tumors (1 paper, 2017). "Similarly, we have recently shown that SLC35F2 is a direct transcriptional target of AR, and that its expression in human prostate tumors is correlated with AR activity and tumor androgen levels." (PMID 28350329, 2017).
triple-negative breast carcinoma (1 paper, 2020). An invasive breast carcinoma which is negative for expression of estrogen receptor (ER), progesterone receptor (PR), and human epidermal growth factor receptor 2 (HER2). "In addition, knockout of SLC35F2 conferred resistance to YM155, most prominently in the triple-negative breast cancer cell lines that were most sensitive to this compound." (PMID 33184288, 2020).
cancer (14 papers, 2013 to 2024). A tumor composed of atypical neoplastic, often pleomorphic cells that invade other tissues. "It is assumed that high levels of SLC35F2 are associated with an increase of YM155 sensitivity in cancer therapy." (PMID 33418944, 2021). "SLC35F2, a transporter of the anti-cancer drug YM155, has been strongly associated with cancer progression." (PMID 33418944, 2021). "SLC35F2 was identified as a carrier of the anti-cancer drug sepantronium, and there were several other studies linking SLC35F2 with the progression of or response to cancer." (PMID 39098524, 2024). "Previously, haploid genetic screening identified SLC35F2 as a YM155 drug-importer generating DNA damage in cancer cells." (PMID 34815782, 2021). "To confront this problem, we screened for DUBs that can upregulate or stabilize SLC35F2 proteins in cancers exhibiting YM155 resistance due to low SLC35F2 expression." (PMID 34815782, 2021). "Unfortunately, there are several cancers having low SLC35F2 levels, which hampers YM155 uptake and results in a low success rate in chemotherapeutics." (PMID 34815782, 2021). "Our approach to inhibiting USP32 to increase chemotherapeutic efficacy can be expanded to YM155-based cancer treatment in cells resistant to YM155 because of low SLC35F2." (PMID 34815782, 2021). "In contrast, low USP32-expressing cancer cells such as PC3, SW480 and HCT116 was associated with relatively high SLC35F2 expression (lanes 1, 2 and 5), suggesting that the USP32 is negatively correlated with SLC35F2 protein in several human cancer cell lines." (PMID 34815782, 2021). "The differential expression patterns of SLC35F2 in several cancer cells induce YM155-mediated DNA damage is poorly understood." (PMID 34815782, 2021). "We determined that USP32, a membrane protein, can confer resistance to cellular uptake of YM155 by destabilizing endogenous expression of SLC35F2 in cancer cells." (PMID 34815782, 2021). "The expression of USP32 and SLC35F2 was negatively correlated across a panel of tested cancer cell lines." (PMID 34815782, 2021). "A series of in vitro and in vivo experiments were conducted to reveal the relationship between USP32 and SLC35F2 on YM155-mediated DNA damage in cancer cells." (PMID 34815782, 2021). "Identifying the factors responsible for preventing the expression of SLC35F2 in YM155-resistant cancer cells is critical to improving the clinical efficacy of small-molecule-mediated cancer therapeutics." (PMID 34815782, 2021). "Sensitivity to YM155 was correlated with SLC35F2 expression across a wide range of cell lines from various cancer types." (PMID 28350329, 2017). "RAB39, a member of the cancer gene Ras family, is close to SLC35F2 in the same chromosomal position (11q22)." (PMID 23879892, 2013). "Recently, a variety of roles of SLC35F2 in cancers have been reported in different kinds of tumors." (PMID 35669242, 2022). "This led us to hypothesize that the high USP32 expression and corresponding low SLC35F2 expression makes cancer cells resistant to YM155 and vice versa in case of sensitive cells." (PMID 34815782, 2021). "Here, CRISPR-based dual-screening strategies (cell viability and protein stabilization) successfully identified USP32 as a novel and bona fide candidate that governs resistance for YM155 uptake by destabilizing SLC35F2 protein levels in a wide range of cancer cells." (PMID 34815782, 2021). "This supports the idea that the C/T mutation in 3′UTR might have an oncogenic effect because it might increase the expression of the oncogene gene SLC35F2, providing some hypothesis that UTR mutation might be involved in cancer progression." (PMID 33418944, 2021). "The results imply that USP32 inhibition in cancer cells resistant to YM155 due to reduced SLC35F2 expression may be an effective YM155-based cancer treatment." (PMID 34815782, 2021).